IL6 (interleukin 6)
Diseases named in the same sentence as IL6 in open-access papers (continued):
Sharing a sentence is not in itself a finding about the gene and the disease.
Insulin resistance (continued). "IL-17 is implicated in insulin resistance through multiple mechanisms, including the activation of inflammatory cells, such as macrophages, which subsequently secrete pro-inflammatory cytokines, such as TNF-α and IL-6." (PMID 40238306, 2025). "Additionally, cytokines such as IL-6 can induce insulin resistance, which hinders the activation of the anabolic Akt/mTOR pathway and consequently impairs muscle protein synthesis." (PMID 41573389, 2025). "There is a positive correlation between circulating IL-6 levels, adiposity, and insulin resistance." (PMID 40284173, 2025). "For instance, the presence of inflammatory cytokines such as interleukin-6 and tumor necrosis factor-alpha has been positively correlated with metabolic disturbances, including insulin resistance and dyslipidemia, which are critical factors in the pathogenesis of cardiovascular diseases." (PMID 40408377, 2025). "Interestingly, IL-6 also promotes insulin resistance, where further worsening of hyperglycaemia exacerbates vascular health." (PMID 41150802, 2025). "On the detrimental side, IL-6 is a key upstream driver of hepatic CRP synthesis and has been linked to endothelial dysfunction, insulin resistance, and systemic inflammatory activation, all of which may accelerate vascular complications in T1D." (PMID 41010714, 2025). "DMT2 and insulin resistance are associated with the overexpression of many inflammatory cytokines, such as tumor necrosis factor alpha (TNF-alpha), IL1 or IL6, which may affect the blood vessels and lead to CVD." (PMID 39940871, 2025). "Moreover, adipose tissue IL-6 levels showed an inverse correlation with insulin sensitivity in obese individuals with type 2 diabetes, and IL-6 released from adipose tissue contributed to hepatic insulin resistance." (PMID 40286055, 2025). "In summary, CDD may improve ovarian function and insulin resistance in PCOS mouse by regulating the IL6/JAK2/STAT3/FOXO4 signaling pathway." (PMID 41573199, 2025). "Although this effect is beneficial to local renal tissues, further research is needed to see whether the decrease in TNF-α and IL-6 reduces insulin resistance." (PMID 40872492, 2025). "The pathophysiology of MetS is strongly linked to adipokine dysregulation, where excessive adipose tissue secretes pro-inflammatory cytokines such as tumour necrosis factor alpha (TNF-alpha) and interleukin-6 (IL-6), exacerbating insulin resistance and hypertension." (PMID 40539174, 2025). "As an alternative and complementary therapy, Cangfu Daotan Decoction may improve ovarian function and ameliorate insulin resistance in PCOS mice by modulating the IL6/JAK2/STAT3/FOXO4 signaling pathway." (PMID 41573199, 2025). "Insulin resistance is often accompanied by the release of more pro-inflammatory cytokines from adipocytes, such as tumor necrosis factor-α, C-reactive protein, and interleukin-6, which are commonly found in EMS patients." (PMID 40004998, 2025). "Additionally, SNPs in genes encoding cytokines such as TNF-α (rs1800629) and IL-6 (rs1800795) have been implicated in the chronic low-grade inflammation characteristic of GDM, exacerbating insulin resistance and metabolic dysfunction." (PMID 40076938, 2025). "Diet and gut microbiota, when altered, cause low-grade systemic inflammation that can lead to insulin resistance through increased levels of pro-inflammatory cytokines in the circulatory system, such as TNF-α, IL-6, β kinase inhibitor (IKKβ), and c-Jun N-terminal kinase (JNK)." (PMID 39997751, 2025). "Insulin resistance is usually associated with high levels of inflammatory and oxidative biomarkers and mediators namely, tumor necrosis factor (TNF)-α, plasminogen activator inhibitor-1 (PAI-1), C-reactive protein (CRP), interleukin-6 (IL-6)." (PMID 40056319, 2025).
Insulin resistance (continued). "Possible explanations include that skeletal muscle has been shown to regulate interleukin-6, tumor necrosis factor-alpha, and insulin resistance, and reduced muscle mass may result in a pro-inflammatory state that can dampen the host immune response to cancer." (PMID 39831184, 2025). "IL-6 and IL-8 reductions in long-term studies likely reflect the central role of these cytokines in chronic low-grade inflammation, particularly in metabolic syndrome, endothelial dysfunction, and insulin resistance." (PMID 40806281, 2025). "Consequently, IL-6 is increasingly recognized as a potential player in the pathogenesis of insulin resistance observed in PCOS." (PMID 40226143, 2025). "Insulin resistance may trigger the release of inflammatory mediators such as tumor necrosis factor-alpha and interleukin-6, potentially compromising airway structural integrity and disrupting central nervous system functions." (PMID 40078414, 2025). "Gut microbiota metabolites may exert therapeutic effects on insulin resistance primarily through the targets IL6, JUN, and PPARG." (PMID 40625623, 2025). "Indeed, these data were subsequently supported indicating increased body weight, impaired glucose tolerance and exacerbated insulin resistance in IL-6 knockout mice." (PMID 41141350, 2025). "Our results are consistent with this, indicating that IL-6 gene variation may also promote high expression of IL-6 and insulin resistance in the Hebei population." (PMID 41293068, 2025). "On the other hand, TNF-α and IL-6 act as pro-inflammatory factors that increase insulin resistance." (PMID 40260393, 2025). "Furthermore, new studies show a robust relationship between systemic insulin resistance, fibrosis stage, hepatic inflammation severity, hepatocyte IL-6 expression, and plasma IL-6 levels." (PMID 40002771, 2025). "The association between the increase in LCN2 concentrations and the development and severity of T2D can be explained through the evidence that demonstrates that LCN2 stimulates the increase of TNF-a and IL-6, cytokines that have been widely recognized as inducers of insulin resistance." (PMID 39808380, 2025). "Patients with T2DM, who have higher baseline insulin resistance, may benefit the most from the acute release of IL-6 during exercise, highlighting its potential as a powerful intervention for metabolic health." (PMID 40091956, 2025). "CDD may improve ovarian function and insulin resistance in PCOS-IR mice by modulating the IL6/JAK2/STAT3/FOXO4 signaling pathway." (PMID 41573199, 2025). "Additionally, IL-6 induces SOCS3-mediated insulin resistance, resulting in a diminished energy supply to muscles and facilitating the accumulation of free fatty acids (FFA), which further exacerbates muscle damage." (PMID 40255379, 2025). "Unlike IL-6 or IL-1β, which are strongly linked to inflammation and insulin resistance in T2D, IL-7 has not been clearly associated with metabolic inflammation or glucose metabolism." (PMID 40804870, 2025). "Dilated and inflamed visceral adipose tissue releases a variety of molecules, including interleukin-6, tumor necrosis factor-alpha, and other pro-inflammatory cytokines, which may contribute to the pathogenesis of insulin resistance and kidney injury." (PMID 40339352, 2025). "Inflammation, often marked by elevated IL-6 levels, contributes to insulin resistance." (PMID 38999025, 2024). "Though IL‐6 is also a myokine and can be anti‐inflammatory when secreted during muscle contraction, the chronic secretion of IL‐6 from adipocytes in the presence of these other inflammatory markers leads to the dysregulation of glucose homeostasis and development of insulin resistance." (PMID 38705872, 2024). "In addition, elevated levels of IL-6 and TNF-α have been linked to systemic insulin resistance, which can potentially contribute to a poorer prognosis in BC patients." (PMID 39342063, 2024). "These M1 ATMφs subsequently secreted TNF-α and IL-6, contributing to insulin resistance." (PMID 39063184, 2024).
Insulin resistance (continued). "There is evidence that TNFα and IL-6 may promote insulin resistance through pathways that hinder the translocation of glucose transporter 4 (GLUT4) to the plasma membrane." (PMID 38317257, 2024). "In addition, HFD increased plasma insulin and eWAT IL-6 levels in Apoe-null mice, both of which indicated insulin resistance." (PMID 39156133, 2024). "Although our current study used a younger age cutoff level (50 years), it revealed a significant elevation of IL6 in aged patients with T2D, denoting the ongoing inflammatory status in such patients, with a potential IL6 effect on exacerbating insulin resistance in those patients." (PMID 38667300, 2024). "Both insulin resistance in type 2 diabetes and immune mediated destruction of pancreatic β cells in type 1 diabetes produce proinflammatory cytokines, such as tumor necrosis factor α and interleukin-6." (PMID 38555533, 2024). "Acute increases in IL-6 in adipose tissue have been shown to improve metabolism and blood glucose levels in obese mice, whereas prolonged elevations of IL-6 may contribute to increased lipolysis and leptin production, as well as insulin resistance." (PMID 39749325, 2024). "MR validated the presence of multiple causative risk factors, particularly APOC3, IL-1, IL6, insulin resistance, height, non-fasting glucose, telomere length, HMGCR, and Niemann-Pick C1-Like 1 (NPC1L1)." (PMID 38601677, 2024). "In vitro and in vivo studies have already shown the ability of IL-6 to induce insulin resistance." (PMID 38734032, 2024). "Several secreted pro-inflammatory and non-inflammatory molecules might contribute to cardiac aging, such as interleukin-1β or interleukin-6 and insulin-like growth factors, by promoting atherosclerosis and insulin resistance, respectively." (PMID 38630423, 2024). "IL-6, an adipokine produced by dysfunctional adipocytes, induces insulin resistance." (PMID 39116155, 2024). "There is a mechanistic relationship between the stimulation of IL-6 and insulin resistance." (PMID 39051061, 2024). "Psoriasis promotes systemic inflammation which, in turn, promotes inflammation in adipose tissue, leading to the release of adipokines (resistin, leptin, and visfatin) and proinflammatory cytokines (IL-6 and TNF-α), which are directly linked to increased insulin resistance." (PMID 38473907, 2024). "Activated TNF-α can elevate plasma FFA levels by promoting lipolysis, inhibit the tyrosine kinase activity of insulin receptors in muscle tissue, and suppress IRS-1 phosphorylation and GLUT4 gene expression, resulting in insulin resistance and also stimulate IL-6 production." (PMID 40302954, 2024). "Additionally, insulin resistance, a factor associated with NAFLD, and levels of liver inflammatory cytokines TNF-α and IL-6, were also ameliorated with supplementation of silymarin." (PMID 38674860, 2024). "Moreover, IL-6 can induce the expression and activity of proinflammatory hsCRP in vivo, which is closely related to the occurrence and progress of insulin resistance and various complications of diabetes." (PMID 39092054, 2024). "IL-6 can induce hepatic insulin resistance by enhancing gluconeogenesis and glycogenolysis." (PMID 39519193, 2024). "However, numerous factors associated with the obese state have the capacity to induce insulin resistance in differentiated 3T3-L1 adipocytes including TNF-α, IL-6, dexamethasone, high insulin, glucosamine, and exposure to hypoxic environment." (PMID 39415617, 2024). "Additionally, in overweight and obese (OB) children, leucine concentrations were significantly elevated, showing a positive correlation with inflammatory markers (CRP, IL-6), SU, visceral adiposity, type 2 diabetes (T2D), insulin resistance, and CVD." (PMID 39027467, 2024). "For instance, IL-6 has been implicated in glucose metabolism and adipocytes’ function, contributing to insulin resistance and systemic inflammation, while the role of TNF-α in promoting insulin resistance is well documented." (PMID 39125408, 2024).
Insulin resistance (continued). "We also found that the IL-6 gene polymorphisms did not appear to play a role in the development of insulin resistance." (PMID 38707766, 2024). "Differences observed here in some inflammatory markers, e.g., IL6, may also explain this phenomenon, as inflammation contributes to insulin resistance and the dysregulation of protein metabolism." (PMID 39275186, 2024). "Patients with heart disease complicated with T2DM may produce inflammatory cytokines, such as tumor necrosis factor-α and interleukin-6, due to intramuscular fat accumulation, which induces insulin resistance and leads to skeletal muscle catabolism." (PMID 38333459, 2024). "Additionally, IL6 and TNFα expression are higher in obese individuals with insulin resistance, with TNFα playing a role in insulin resistance." (PMID 38339282, 2024). "Furthermore, expression of IL-6 can lead to insulin resistance, which effectively dampens muscle protein synthesis." (PMID 38892810, 2024). "The biological mechanisms underlying MASLD leading to HCC involve the release of inflammatory cytokines (such as TNF-α, IL6) and reduced adiponectin levels that promote insulin resistance, which in turn inhibits fatty acid oxidation, leading to DNA damage and mutations." (PMID 38987736, 2024). "Furthermore, pharmacological reduction in insulin resistance has been shown to be effective, as metformin, the most prescribed antidiabetic drug, reduced the burden of the disease by reducing IL-6-induced inflammation, oxidative stress, and insulin resistance." (PMID 38255279, 2024). "Additionally, interleukin-6 (IL-6) has been shown to enhance insulin resistance, liver vulnerability, hepatocyte apoptosis, and NASH progression." (PMID 39055878, 2024). "In summary, leptin, TNF-α, and IL-6 may participate in progressive maternal insulin resistance in pregnancy, whereas the insulin sensitivity-enhancing effect of adiponectin diminishes as its maternal concentrations decrease." (PMID 39519203, 2024). "In addition, smoking is associated with increased pro-inflammatory cytokines, such as tumor necrosis factor-alpha (TNF-α) and interleukin-6 (IL-6), which can further contribute to insulin resistance." (PMID 38894993, 2024). "This is because IL-6 mediates insulin resistance by regulating fat and glucose metabolism." (PMID 39139641, 2024). "IL-6 is considered an inflammatory cytokine that increases hepatic insulin resistance." (PMID 38543143, 2024). "Moreover, significant reductions in the TNF-α, IL-6, MDA, and COX-2 levels confirmed that inflammation and oxidative stress have been associated with insulin resistance." (PMID 38892660, 2024). "IL-6 induces insulin resistance in adipose tissue and liver and may synergize with proinflammatory cytokines to produce β-cell damage." (PMID 38504163, 2024). "IL-6 also provokes insulin resistance and hyperglycemia by increasing CRH and ACTH release." (PMID 39682557, 2024). "White adipose tissue stresses or lipopolysaccharides increase NF-κB and c-Jun N-terminal kinase signaling, upregulate the production of inflammatory cytokines such as TNF-α and IL-6, and promote insulin resistance in adipocytes and macrophages via TLR4/TLR2 activation." (PMID 38292473, 2024). "Visceral adipocytes produce and release a series of adipokines, including interleukin-6, adiponectin, and leptin, which may lead to increased insulin resistance." (PMID 39348367, 2024). "Moreover, excessive adipose tissue deposition promotes insulin resistance, impaired glucose and lipid metabolism, and systemic inflammatory reactions, including the release of interleukins (IL‐6, 10, 13, 14), TNF, and diffuse macrophage activation." (PMID 38767024, 2024). "IL-6 disrupts insulin signaling by activating pathways that phosphorylate insulin receptor substrates (IRS), leading to reduced insulin receptor activity and insulin resistance, a hallmark of T2DM." (PMID 39857603, 2024).
Insulin resistance (continued). "In addition, elevated IL-6 levels induce insulin resistance and hyperglycemia by mobilizing glucose from hepatic glycogen stores." (PMID 39682557, 2024). "Similarly, IL-6 stimulates the occurrence of insulin resistance and high blood sugar levels by triggering the release of CRH and ACTH." (PMID 39682557, 2024). "In addition, insulin resistance and glucose intolerance are observed in mice with liver-specific IL-6Rα KO, resulting in increased IL-6, IL-10, and TNF-α expression." (PMID 38999780, 2024). "While molecular pathways connecting IL-6 to insulin resistance in the adipose tissue remain elusive, stimulation of IL-6 synthesis may reflect a compensatory response to impaired glucose metabolism." (PMID 39723211, 2024). "Indeed, IL-6 mRNA expression was demonstrated in human subcutaneous adipose tissue and elevated IL-6 mRNA levels measured in individuals with insulin resistance." (PMID 39723211, 2024). "The redistribution of fat (e.g., loss of subcutaneous fat and increased visceral adiposity) promotes a chronic inflammatory state, marked by increased TNF-α and IL-6, which not only worsens insulin resistance but also disrupts bone health by increasing bone resorption and reducing bone formation." (PMID 39339002, 2024). "Recent evidence shows that IL-6 may have a possible disease-limiting role in liver inflammation and remodeling through the induction of miR-223 secretion by myeloid cells, insulin resistance, and adipose tissue macrophage accumulation in animal models." (PMID 38542310, 2024). "Moreover, adipose tissue produces high levels of proinflammatory cytokines, including monocyte chemotactic protein-1 (MCP-1), IL-6, and IL-1, which exacerbate insulin resistance." (PMID 39682557, 2024). "Additionally, in vivo studies showed that asprosin increased endoplasmic reticulum stress, glucose intolerance, insulin resistance, and the flow of pro-inflammatory cytokines (monocyte chemoattractant protein-1, IL-6, and TNF)." (PMID 38217801, 2024). "In addition, IL-33 treatment of adipocytes and ATMs induces the production of IL-5, IL-6 and IL-13 which can exert protection against insulin resistance." (PMID 36994095, 2023). "Another mechanism proposed by our hypothesis is that the chronic inflammatory state in DM patients might aggravate insulin resistance via inflammatory mediators such as interleukin-6 (IL-6) and nuclear factor kappa B (NF-kB)." (PMID 37299386, 2023). "Importantly, oxidative stress can induce insulin resistance in adipocytes and dramatically increase IL6 secretion in 3T3-L1 cells 3-fold." (PMID 37298352, 2023). "However, low and high dosage administration of vitamin A decrease TNF-α and IL6 on obese adults; therefore, reducing insulin resistance, and improving energy expenditure." (PMID 36776154, 2023). "It decreases fat mass related to reduced insulin resistance, tumor necrosis factor α (TNFα), interleukin-6 (IL-6), as well as decreased activity of the c-Jun N-terminal Kinase (JNK) and IκB kinase subunit β (IKKβ); thus, in liver and muscle, glutamine improves insulin signaling." (PMID 37696865, 2023). "This inflammatory state increases the secretion of proinflammatory cytokines (adipokines), such as tumour necrosis factor alpha (TNFα), interleukins 1 and 6 (IL-1 and IL-6) and leptin, which generates insulin resistance, the inhibition of protein synthesis and an increase in muscle catabolism." (PMID 36626317, 2023). "Besides, mitochondrial damage produces a large amount of ROS, which induces the release of inflammatory factors [such as TNF-α, interleukin 1β (IL-1β) and IL-6] and disrupts pancreatic β-cell function, further aggravating insulin resistance." (PMID 37828472, 2023). "In addition, this cytokine orchestrates the mobilization of other inflammatory mediators, e.g., IL-6 contributing to insulin resistance and dyslipidemia." (PMID 38139276, 2023).